IL18 (interleukin 18)
Diseases named in the same sentence as IL18 in open-access papers (continued):
Sharing a sentence is not in itself a finding about the gene and the disease.
tumor (continued). "Corroborating these clinical data, preclinical studies of IL-18-armored CAR and T cell receptor-engineered T cells have demonstrated enhanced anti-tumor activity in several xenograft and syngeneic mouse cancer models." (PMID 41728085, 2026). "IL-6 enhances immune cell recruitment and promotes tumor progression by inducing epithelial-to-mesenchymal transition (EMT) and angiogenesis, while IL-1β and IL-18 are key pro-inflammatory cytokines activated by the NLRP3 inflammasome pathway." (PMID 40218944, 2025). "DLL3’s tumor-specific expression in SCLC offers a viable target, while engineering strategies such as cytokine-secreting “armored” CARs (e.g., IL-12 or IL-18 producers) show promise in overcoming TME resistance." (PMID 40496850, 2025). "Cytokines secreted by type 1 helper T cells (Th1), such as interleukin (IL)-2, IL-12, IL-18, interferon γ (IFN-γ), and tumor necrosis factor (TNF), participate in anti-tumor defense." (PMID 41561739, 2025). "For instance, IL-18-secreting DLL3 CAR-T cells counteract TME immunosuppression by enhancing T-cell persistence and reversing exhaustion, achieving complete tumor regression in preclinical models." (PMID 40496850, 2025). "Following chemotherapy, macrophages secrete interleukin-18 (IL-18), which in turn upregulates L-amino acid transporter protein 2 (LAT2) expression in tumour cells." (PMID 40598593, 2025). "Mechanistically, IL-18 stimulates IFN-γ production, which subsequently activates natural killer cells and CD8+ T lymphocytes, significantly enhancing their tumour-specific cytolytic activity." (PMID 40738927, 2025). "IL-18 has been shown to enhance IFN-γ production by T and NK cells, promote cell death, and inhibit tumor progression." (PMID 40115022, 2025). "These IL-18-expressing CAR-T cells exhibited potent anti-tumor effects, not only through direct cytotoxicity but also by modulating the tumor microenvironment." (PMID 41584600, 2025). "N1 TANs restrict tumor growth by enhancing IL-18 expression in natural killer (NK) cells through INF-1 secretion and by directly inducing tumor cell death via myeloperoxidase, ROS, and related mediators." (PMID 41320679, 2025). "In summary, IL-18 plays a pivotal role in the immunological enhancement of CAR-T cell therapy, promoting both direct anti-tumor activity and the recruitment of additional immune effectors, thereby improving therapeutic outcomes in cancer immunotherapy." (PMID 41584600, 2025). "Similar to other cytokines previously studied, IL-18 plays a significant regulatory role in macrophages and CD8+ T cells within the PC microenvironment, thereby contributing to tumor progression." (PMID 40948749, 2025). "IL-18 expression in CAR cells enhances proliferation, recruits and activates bystander immune populations, and remodels the tumor microenvironment toward a pro-inflammatory state." (PMID 41584600, 2025). "GSDME-mediated pyroptosis significantly increases tumor infiltration of CD8+ T cells by releasing IL-1β and IL-18, effectively reprogramming the immunosuppressive TME." (PMID 41267084, 2025). "Mechanistic studies involved the levels of cellular ROS, IL-1β, IL-18 and the expression of caspase-1/3/7/9-GSDMD/E in both cell and tumor tissues were determined by ELISA, immunohistochemistry, Western blot and qRT-PCR." (PMID 40604924, 2025). "Its activation triggers the release of inflammatory cytokines, such as IL-1β and IL-18, enhances CD8+ T cell infiltration, and improves chemosensitivity, thereby exerting potent tumor-suppressive effects." (PMID 40568597, 2025). "In clear cell renal cell carcinoma, IL-1β+ and IL-18+ Tregs co-localize with MRC1+FOLR2+ TAMs at tumor-normal interfaces, forming a positive feedback loop that sustains synergistic pro-tumor effects." (PMID 41417432, 2025). "Specifically, the expressions of CXCL10, ICMA1, IL18, ITGAL, SOCS3, and TLR3 were higher in tumor tissues compared to their corresponding paracancerous tissues." (PMID 40838069, 2025).
tumor (continued). "Our findings demonstrate a significant increase in cytokines such as IL-2, IL-18, GM-CSF, IFN-γ, and MCP-1 following tumor removal." (PMID 40711287, 2025). "M1 macrophages can secrete pro-inflammatory molecules such as IL-1, IL-18, and TNF-α, which exert anti-tumor effects." (PMID 40704015, 2025). "For instance, IL‐18 amplification in CNV, which correlated with increased IL‐18 protein expression, plays a key modulatory role in the tumour microenvironment of non‐small‐cell lung cancer." (PMID 41292185, 2025). "Specifically, IL-18 derived from CD4+ T cells or introduced exogenously has been shown to promote the proliferation and anti-tumor activity of CD8+ T cells and CAR-T cells." (PMID 40141358, 2025). "Pan-cancer analysis showed that IL18 and CCL5 proteins were overexpressed in GBM compared with other tumor types." (PMID 41155216, 2025). "By analysing IL1β, IL10, IL18, TNF-α, TLR4, GATA3, and CD68 expression in 50% of PCa HHV-infected FFPE with an elevated inflammation index (61.8%/21), we detected hyper-expressed levels of IL1β, IL18, and TNF-α in the tumour microenvironment." (PMID 40430084, 2025). "The expression profiles of IL1β, IL10, IL18, TNF-α, TLR4, GATA3, and CD68 in HHV-infected PCa FFPE biopsies indicated an inflammatory environment conducive to immune alteration and potential tumour progression." (PMID 40430084, 2025). "Our previous studies demonstrated a significant increase in TNF-α, IL-6, IL-18, IL-1β, and INF-γ in the skeletal muscle of tumor-bearing animals, which normalized after treatment with withaferin A (WFA)." (PMID 39996717, 2025). "This inflammatory state promotes the release of cytokines (e.g., IL-1β, IL-6, IL-10, IL-18, TNF-α) and growth factors that facilitate tumor cell proliferation, invasion, and angiogenesis, while simultaneously impairing immune surveillance." (PMID 41114747, 2025). "P.g. induces macrophage polarization into tumor-associated M2, upregulating gene expression of pro-tumoral molecules (suprabasin, IL-1R2, IL-18, and TGF-α) while suppressing multiple anti-tumor cytokines (TNF-β, IFN-β, TRAIL, and TNF-α) in Cal-27 cells." (PMID 40924302, 2025). "Senescent tumor cells can also secrete an immunosuppressive SASP, including interleukin-18, CXCL-1, and CCL-20, by CDK4/6is, increasing the infiltration of MDSCs and leading to an immunosuppressive microenvironment." (PMID 41463246, 2025). "Our proteomic analysis, based on data from the Clinical Proteomic Tumor Analysis Consortium (CPTAC), focused on CCL5, IL18, and FCER1G." (PMID 41155216, 2025). "IL-18 upregulates TLR4 expression in PTCL cells, activating the downstream NF-κB-mediated anti-apoptotic pathway to promote tumor proliferation and chemoresistance." (PMID 41267084, 2025). "The secretion of IL-18 by NLRP3 in Kupffer cells plays a key role in promoting NK cell maturation and enhancing their tumor-killing activity." (PMID 40141358, 2025). "Immunofluorescence staining in tumour-bearing liver from KPC mice and littermate controls confirmed that the CCR5 ligands CCL3, CCL4 and CCL5, and the cytokines IL-12, IL-15 and IL-18 were produced by KCs in peritumoural liver." (PMID 38326607, 2024). "IL-12, IL-18, and IL-15 are the most widely used cytokines that enhance the cytotoxic efficacy of TRUCK CAR-T cells and reduce tumor mass." (PMID 39312080, 2024). "Treatment strategies that were the most effective in tumor destruction, namely NT GSDMD combined with IL-1β, IL-18, or IL-12, showed similar tissue characteristics." (PMID 39737979, 2024). "Common cytokines used in TRUCKs include interleukin (IL)-2, IL-15, and IL-18, which enhance the immune response against solid tumours and extend the persistence of CAR-T cells within the tumour microenvironment." (PMID 39596267, 2024). "AIM2 displayed antitumor activity in tumor cells, and within HCC cells, the expression of Caspase‐1 and the concentrations of IL‐1β and IL‐18 were positively correlated with AIM2 expression." (PMID 39222064, 2024).
tumor (continued). "IL-18 can also induce hypoxia-inducible factor-1α (HIF-1α), which mediates tumor progression and can encourage tumor metastasis." (PMID 39451257, 2024). "Consistently, quantification of activated natural killer (NK) cells and CD8+ T cells in the metastatic liver showed that they were also preferentially enriched at the tumour margin, next to KCs expressing CCL3, CCL4, CCL5, IL-12, IL-15 and IL-18." (PMID 38326607, 2024). "Remarkably, the whole tumor transcriptome analysis revealed that IL-12 enriched pyroptosis and NT GSDMD + IL-1β + IL-18 treatments with different therapeutic outcomes exhibit enrichment in interferon signaling." (PMID 39737979, 2024). "The correlation between tumor progression and epithelial expression of NLRP6 and IL18 establishes NLRP6 and IL18 expression levels in sporadic CRC cells as robust predictors of patient outcomes." (PMID 38892354, 2024). "Pyroptosis also impacts the tumor microenvironment in HCC, with cytokines such as IL-1β and IL-18 playing roles in regulating immune responses." (PMID 39544286, 2024). "Probes to detect the following RNAs were used: IL-18, ADGRE1 to visualize macrophages, and mouse mesothelin or human CD19 for tumor antigen detection of PDA7940b tumors or B16-huCD19 tumors, respectively." (PMID 38730243, 2024). "Based on the level of circulating IL-18 and combined with neutrophil count, they demonstrated that patients receiving ICI therapy that go into true tumor progression can be distinguished from patients going into “pseudoprogression”." (PMID 39769266, 2024). "Further, we developed IL-18 secreting CART and demonstrate enhanced anti-tumor function in preclinical models." (PMID 38730243, 2024). "Armoring with GzB-IL18 enhances cytolytic activity, proliferation, interferon (IFN)-γ release, and anti-tumor efficacy by a similar magnitude to constitutively active IL18." (PMID 38745414, 2024). "It has been observed that cytokines such as IL-2, IL-12, IL-15, IL-18, and TGF-β can modulate the anti-tumor immune response mediated by NK cells, offering new strategies and choices for immunotherapy by regulating the function and activity of NK cells." (PMID 39221244, 2024). "In present study, compared with tumor model group, the expression of NLRP3, caspase 1, GSDMD and the level of IL-1β and IL-18 in XRZYBXD high dose group were increased." (PMID 40046008, 2024). "Further analysis of the differential expression of IL-1 family and related genes in normal tissues and HPV- and HPV+ tumor tissues revealed that IL-1α, IL-1β, IL1R1, IL1R2, IL1RL1, IL1RAP, IL1F10, IL-18 and CASP1 were highly expressed in HPV- tumors." (PMID 39461030, 2024). "We first evaluated nutrient transporter expression in IL18-armored αβ and γδ pCAR-H/T+ T cells, either after expansion for 3 weeks or following two additional re-stimulation cycles on MDA-MB-468 tumor cell monolayers." (PMID 38745414, 2024). "P2X7 activation by eATP also enhances anti-tumor effects through cGAMP transfer and STING activation, and the eATP–P2X7–inflammasome–IL18 axis reduces macrophage numbers in tumors while improving T-cell responses." (PMID 39456655, 2024). "In one study, autologous tumor cell vaccines via EBV/liposomes were designed to secrete IL-12 and IL-18 (B16/mIL-12+mIL-18), and repeated immunization showed strong tumor inhibition in a B16 melanoma model, accompanied by high IFN-γ production." (PMID 39451566, 2024). "Once tumor was established for 11 days, animals were treated with i.p. pCAR-H/T + nil CAR T cells or IL18-armored derivatives." (PMID 38745414, 2024). "Pyroptosis induced by caspase-4/GSDMD can also promote the release of inflammatory factors such as IL-1β and IL-18, as well as recruit CD8+ T cell infiltration, thereby activating anti-tumor immunity." (PMID 39062587, 2024).
tumor (continued). "Preclinical studies have verified that IL-18 TRUCKs CAR-T cells targeting GD2 induced monocytes recruitment, which helped reprogram the tumor stroma into a more favorable environment, thus making CAR-T cell therapy for solid tumors more effective." (PMID 38622705, 2024). "Given its potentiating effects on anti-tumor activity, particularly in the case of CAR γδ T cells, we next evaluated metabolic effects of IL18 armoring." (PMID 38745414, 2024). "The secreted cytokines IL-7, IL-12, IL-15, or IL-18 not only enhance the survival capacity of CAR–T cells and augment their cytotoxic activity but also attenuate the immunosuppressive tumor microenvironment." (PMID 39220130, 2024). "After a literature review, we collect factors that directly regulate the function of NK cells, and the gene list is IL2, IL15, IL18, IL21, all of which promote NK cell-mediated tumor death, while IL6, TGFβ and TNFα promote NK cell exhaustion." (PMID 38159250, 2023). "Members of the IL1 family, including IL1B, IL33, and IL18, are upregulated in the GPBAR1 tumors and are generally identified as contributors to tumor immunosuppression." (PMID 36834607, 2023). "The study has shown that increased IL-18 production induced C-X-C Motif Chemokine Ligand 16 (CXCL16) secretion, which recruited immunosuppressive bone MDSCs and enhanced tumor cell proliferation and migration." (PMID 37833958, 2023). "Moreover, CAR-T cells secreting IL-7, IL-12, IL-15, IL-18, IL-33, and IL-36γ have also exhibited improved persistence or anti-tumor ability in preclinical or clinical trials; however, the continuous expression of pro-inflammatory cytokines such as IL-12 may lead to systemic toxicity." (PMID 37596653, 2023). "We assessed the concentrations of proinflammatory factors (IL-1β, IL-18, HMGB1) in tumours or in serum." (PMID 37673934, 2023). "Inspired by this point, we analysed the inflammation in TIOs+NIR1 treated mice, as shown, compared with TIOs+NIR3 treatment, the IL-1β, IL-18 and HMGB-1 release in tumour beds were almost four fifths lower." (PMID 37673934, 2023). "In a murine metastatic SCLC model, IL-18 production increased the activation of both CAR T cells and endogenous tumor-infiltrating lymphocytes." (PMID 36951942, 2023). "The release of IL-18 mediated by the NLRP3 inflammasome increases the expression level of effector T cells, enhancing the effect of anti-tumor immunity." (PMID 37705746, 2023). "To investigate the relationship between IL-18 and A2AR expression in this context we inoculated A2AR eGFP reporter mice with either IL-18 expressing or control MC38 tumors and assessed the phenotype of tumor-infiltrating lymphocytes." (PMID 37914685, 2023). "Therefore, tumor proliferation might be promoted in Il18−/− mice." (PMID 38139000, 2023). "By inhibiting NLRP3-dependent IL-18, RAI16 maintained intestinal homeostasis and inhibited tumor development." (PMID 37833958, 2023). "Results indicated that compared with that in tumour cells of NSCLC, IL-18 was significantly up-regulated in CAFs." (PMID 37871286, 2023). "Nigericin displayed an anti-tumor impact in tumor cell lines with modest NLRP3 stimulation and IL-1β and IL-18 production." (PMID 37715239, 2023). "These experiments confirmed that IL-18 was a strong inducer of A2AR expression in vivo, and anti-tumor effects were even greater in A2AR knockout mice, highlighting the potential for combination therapy targeting the A2AR in conjunction with IL-18 therapy." (PMID 37914685, 2023). "As with the results obtained with IL-18 and PD-1 co-blocking treatment, combining PD-1 and CXCR4 blocking increased CD8+ T-cell infiltration of the tumors and enhanced the survival of the tumor-bearing mice." (PMID 37176035, 2023).
tumor (continued). "These inflammatory factors include pro-inflammatory cytokines IL-1β, IL-18, and DAMPs such as ATP, DNA, or HMGB1, and in doing so they regulate the proportions of tumor-infiltrating immune cells such as T cells, NK cells, DCs, monocytes, and MDSCs." (PMID 36831197, 2023). "The ELISA results illustrate the robust induction of IL-1β, IL-18 and HMGB1 production, an indicator of pyroptosis-induced ICD, in both tumor and serum samples following treatment with GSDMBNT mRNA@LNPs alone or in combination with a-PD1." (PMID 37454146, 2023). "This orchestrated process involves the release of inflammatory factors, such as IL-18 and IL-1β, which attract dendritic cells and CD8+ T cells into the tumor tissue, activating antitumor immunity and hindering tumor progression." (PMID 38066523, 2023). "Therefore, tumor growth might be increased in Il18−/− mice compared with Il18+/+ mice." (PMID 38139000, 2023). "MSCs are able to deliver a variety of cytokines and growth factors to the tumor site that were identified as anti-tumor agents, comprising IFN-α, IFN-β, IFN-γ, IL-2, IL-7, IL-12, IL-15, IL-18, IL-25, and NK4, an antagonist of HGF." (PMID 37686315, 2023). "These cells can be stimulated in an inflammatory or tumor microenvironment by antigens secreted by the tumor or pathogen, IFN-γ itself via positive feedback, or IL-12, IL-15, and IL-18 to activate IFN-γ production." (PMID 36835413, 2023). "Interferon and TGF-β can directly or indirectly inhibit tumor cell growth, TNF and various chemokines play a role by promoting angiogenesis, and IL-18 can activate NF-κB signal, induce cancer cell proliferation and invasion, and prevent cell apoptosis." (PMID 37091857, 2023). "In summary, the characteristics of IL-18 in the TME and tumor progression make it an attractive target for cancer therapy." (PMID 38066523, 2023). "Analysis of tumor microenvironment gene sets also revealed that TGF-β signaling, matrix metalloproteinases, IL-18 signaling and TH17 cell differentiation signaling pathways were significantly enriched." (PMID 36579622, 2023). "IL-18 and IFN-γ are both pro-inflammatory cytokines, and both can exert anti-tumor effects by promoting the production of anti-cancer cytokines and enhancing the killing of tumors by immune cells." (PMID 37513021, 2023). "Nevertheless, IL-18 also promotes IFN-γ production in Th1 cells and NK cells, thus enhancing the anti-tumor ability of CD8+ cells." (PMID 36823153, 2023). "In a preclinical study, XmAb143 (IL18-Fc) promoted NK and T lymphocyte expansion and IFN-γ secretion in huPBMC-engrafted NSG mice (GvHD model) and demonstrated tumor growth inhibition, T-cell proliferation and activation in CD34+ humanized mice." (PMID 37483629, 2023). "For instance, a study showed that IL‐18 and CXCL10 are correlated with the degree of tumor response in 32 NSCLC patients who received PD‐1/PD‐L1 inhibitors." (PMID 37062076, 2023). "IL-18 stimulated persistence and activation of both CAR T cells and tumor-reactive endogenous T cells, as well as myeloid cells in the TME." (PMID 36951942, 2023). "IL-18 has been reported to synergistically induce IFN-γ production by CD8+ T and NK cells with IL-12, followed by a direct tumor-killing function through the Fas-FasL and TRAIL mechanisms." (PMID 37513021, 2023). "To investigate the role of IL18 in RCC, we firstly analyzed the expression of IL18 in tumor tissues and paired normal adjacent tissues." (PMID 36707882, 2023). "Several pro-inflammatory cytokines released by M1-activated macrophages, including IL-12, IL-15, IL-18, and TNF-α, are critically involved in the improvement of NK cell anti-tumor function." (PMID 37298470, 2023). "Only concomitant IL-18 and PD-1 blocking decreased MDSC infiltration of the tumor and increased the anti-tumoral T-cell responses, slowing tumor progression." (PMID 37176035, 2023).